CCDC6 (coiled-coil domain containing 6)
Diseases named in the same sentence as CCDC6 in open-access papers (continued):
Sharing a sentence is not in itself a finding about the gene and the disease.
cholangiocarcinoma (5 papers, 2018 to 2025). A carcinoma that arises from the intrahepatic biliary tree (intrahepatic cholangiocarcinoma) or from the junction, or adjacent to the junction, of the right and left hepatic ducts (hilar cholangiocarcinoma). "We further evaluated the CCDC6 expression difference between the normal tissues and tumor tissues of cholangiocarcinoma and liver hepatocellular carcinoma using GEPIA and UALCAN, and we found that both tumor tissues overexpressed CCDC6." (PMID 36186907, 2022). "In the pathway enrichment analysis of CCDC6 from our previous study, we observed that CCDC6 may exert its function through the ErbB pathway in cholangiocarcinoma (CCA)." (PMID 41035371, 2025). "The paired analysis results from the TCGA database further confirmed that CCDC6 is highly expressed in cholangiocarcinoma and liver hepatocellular carcinoma (all p<0.001) compared with the expression in the corresponding normal controls, the difference was highest in the cholangiocarcinoma." (PMID 36186907, 2022).
ovarian carcinoma (5 papers, 2013 to 2026). A malignant neoplasm originating from the surface ovarian epithelium. "Here, we provide preclinical data demonstrating an association between olaparib sensitivity and the CCDC6 gene product depletion in ovarian cancer, indicating CCDC6 as one of these biomarkers." (PMID 35964058, 2022). "In this work, we reported that in ovarian cancer cells, a physical or functional loss of CCDC6 results synthetic lethal with the PARP-inhibitors drugs, by affecting the HR repair." (PMID 35964058, 2022). "Around 3% of ovarian carcinomas in COSMIC have CCDC6 mutations." (PMID 41417832, 2026). "Notably, CCDC6 is mutated in about 3% of ovarian cancer cases [Catalogue of Somatic Mutations in Cancer (COSMIC)], with three specific missense mutations (L217P, A226S, and P442S) identified at a low percentage in HGSOC." (PMID 41417832, 2026). "The physical or functional loss of CCDC6 could also overcome the acquired resistance to PARPi treatment in ovarian cancer patients." (PMID 35964058, 2022). "Suppression of CCDC6 expression has demonstrated synergistic effects with targeted therapies in ovarian cancer." (PMID 41035371, 2025). "CCDC6 was aberrantly expressed in various malignant tumours, including gastric, lung and ovarian cancers, with its expression closely correlated with tumour progression." (PMID 41035371, 2025). "While MOB1A and CCDC6 were significantly over-expressed in ovarian cancer samples, expression of these genes, as well as of TUBB, PRKAR1A, and SOCS3 appeared to be expressed at high levels in multiple healthy tissue sites." (PMID 36943460, 2023). "To do this, we reduced CCDC6 protein levels in ovarian cancer cells using the USP7 inhibitor P5091 and evaluated sensitivity to various olaparib concentrations." (PMID 35964058, 2022). "We also unravelled a role for CCDC6 as predictive marker of PARPi sensitivity in ovarian cancer, and the impact of CCDC6 downregulation in overcoming PARPi resistance in these tumours." (PMID 35964058, 2022). "Together these results demonstrate that the genetic or pharmacological modulation of the CCDC6 protein levels in ovarian cancer cells affects sensitivity to the anti-cancer PARPi as well as to the recently developed PARGi." (PMID 35964058, 2022). "Here we unravelled a role for CCDC6 gene product in PARPi sensitivity of ovarian cancer cells via the PP4c-mediated modulation of HR proficiency." (PMID 35964058, 2022). "Here, we investigated if CCDC6 expression would influence how sensitive a panel of ovarian cancer cell lines was to PARPi and PARGi." (PMID 35964058, 2022). "This is because in the BRCA2 mutant PEO1 ovarian cancer cells only a barely detection of CCDC6 protein was observed at immunoblot, likely due to an enhanced CCDC6 proteolysis." (PMID 35964058, 2022). "In ovarian cancer, inactivation of the CCDC6 protein signals a defect in DNA repair, known as HRD." (PMID 41417832, 2026). "We used the well-known PEO1 and PEO4 cells, which represent naturally occurring CCDC6 null and CCDC6 competent ovarian cancer cell types, respectively, that display differing protein levels despite having equivalent amounts of CCDC6 transcripts, to test this hypothesis." (PMID 35964058, 2022). "We are currently conducting biochemical studies and analysing additional ovarian cancer samples, as well as patient-derived xenografts, enriched for BRCA1/2 mutants, to understand whether the BRCA1/2 mutational status is associated with or determines the CCDC6 increased turnover." (PMID 35964058, 2022). "Nevertheless, when these ovarian cancer cells were challenged with different concentration of PARGi and their vitality assessed by MTT assays, the change of PARGi sensitivity upon CCDC6 downregulation appeared evident." (PMID 35964058, 2022). "Although each alteration is infrequent, ROS1 fusions with many kinds of 5′ partner genes (CCDC6, CD74, EZR, KDELR2, LRIG3, SDC4, SLC34A2 and TPM3) have been reported in lung, brain, biliary tract, and ovarian cancers." (PMID 23418494, 2013).
thyroid tumours (5 papers, 2012 to 2023). "The structural variant (SV) analysis identified the other four thyroid tumours with inversions that resulted in CCDC6‐RET fusions." (PMID 37317665, 2023). "CCDC6 was originally identified in chimeric genes as caused by chromosomal translocation involving the RET protooncogene in some thyroid tumors." (PMID 23145146, 2012). "Based on a public dataset GSE199023, zebrafish thyroid tumors transfected with BRAFV600E oncogenes showed higher expression of STRA6 as compared to those transfected with CCDC6-RET fusion." (PMID 36843593, 2023). "CCDC6, encoded by Coiled Coil Domain Containing 6 gene, was initially detected after chromosomal translocation of RET in some thyroid tumors." (PMID 35978072, 2022). "When rearranged with RET, CCDC6 contributes aminoterminus portions corresponding to 101aa, identified in most of the cases of lung and thyroid tumours, or portions corresponding to 150aa or 293aa, reported at very low percentage in thyroid tumours." (PMID 29455670, 2018). "CCDC6 has been also reported to be rearranged with genes different from RET in thyroid and non-thyroid tumours." (PMID 23145146, 2012).
breast carcinoma (4 papers, 2014 to 2023). "Paratala and colleagues profiled RET fusions in breast cancer and identified CCDC6-RET, NCOA4-RET and RASGEF1A-RET." (PMID 34650924, 2021). "Fusion partners of FGFR2 reported specifically in breast cancer are AFF3, CASP7 and CCDC6, while partners identified in other cancers include TACC and KIAA family members, PPHLN1, NTRK1, BICC1, AHCYL1, OFD1 and SLC45A3." (PMID 34344433, 2021). "Among them, ETV6-NTRK3, CCDC6-RET, NCOA4-RET and FGFR3-TACC3 have been reported in breast cancer previously." (PMID 34650924, 2021). "Of note, the vast majority of the 27 fusions we identified were rearranged with novel partners, with only 4 previously reported in breast cancer, including ETV6-NTRK3, CCDC6-RET, NCOA4-RET and FGFR3-TACC3." (PMID 34650924, 2021). "In addition, we detected previously identified RET fusions in new tumour indications, including a single CCDC6–RET fusion in colon adenocarcinoma and a single ERC1–RET fusion in breast cancer." (PMID 25204415, 2014).
lymph node metastases (4 papers, 2017 to 2025). "Specifically, CCDC6 overexpression was significantly associated with poor prognosis in iCCA patients and was markedly elevated in cases of advanced disease or lymph node metastasis." (PMID 41035371, 2025). "Patients with extrathyroidal extension and lymph node metastases were characterized by the presence of a BRAFV600E mutation and CCDC6-RET fusion." (PMID 31620364, 2019). "Remarkably, CCDC6 low levels indicate poor prognosis, correlating positively with the presence of lymph node metastasis and negatively with disease free survival." (PMID 28653990, 2017). "Her lymph node metastases (LNM) were positive only for the CCDC6/RET fusion gene." (PMID 37882481, 2023).
prostate carcinoma (4 papers, 2017 to 2020). A carcinoma that arises from epithelial cells of the prostate gland. "The immunoblot with anti-CCDC6 antibody indicated that the CCDC6 half life was reduced upon the P5091 treatment in these prostate cancer cell lines." (PMID 28415632, 2017). "Thus, the CCDC6 deficiency, accompanied by the HR-DNA repair defects, determines sensitivity to PARP-inhibitors, in lung, colon and prostate cancer cells, as recently demonstrated." (PMID 30786932, 2019). "The inhibition of USP7, able to affect the stability of the AR isoforms but also that of proteins like CCDC6 involved in HR impairment, might be able to sensitize hormone-sensitive and hormone-resistant prostate carcinoma to PARP inhibition." (PMID 31242618, 2019). "Here we suggest that the lethal effect obtained by the combined treatment of the PARP inhibitors with the USP7 inhibitors in prostate cancer cells that express CCDC6, and its de-ubiquitinating enzyme USP7, may be considered an “induced synthetic lethality”." (PMID 28415632, 2017). "Moreover, in these cells, we have investigated whether the inhibition of the deubiquitinase USP7, by lowering the CCDC6 levels and impairing the homologous recombination (HR) processes may increase the prostate cancer cells sensitivity to PARP inhibitors." (PMID 28415632, 2017). "In prostate cancer, targetable levels of USP7 and CCDC6 have been detected in a wide series of prostate tumor biopsies via IHC staining." (PMID 31242618, 2019). "We scored and correlated CCDC6 and USP7 expression levels in a prostate cancer tissue microarray (TMA)." (PMID 28415632, 2017). "Here, we correlated the expression levels of CCDC6 and USP7 proteins in primary prostate cancers (PC)." (PMID 28415632, 2017). "CCDC6 attenuation in prostate cancer cells confers sensitivity to Olaparib, independent of their castration resistance status." (PMID 31242618, 2019). "Then, CCDC6 and USP7 may be predictive biomarkers for the combined treatment of USP7 and PARP-inhibitors in advanced prostate cancer." (PMID 31242618, 2019). "Thus, CCDC6 and USP7 represent predictive markers for the combined treatment of the USP7-inhibitors and PARP-inhibitors in advanced prostate cancer." (PMID 28415632, 2017). "Finally, we propose that the assessment of CCDC6 and USP7 tissue expression could provide us with a predictive tool to manage prostate cancer patients at advanced stage." (PMID 28415632, 2017).
thyroid (4 papers, 2012 to 2024). "The tumor suppressive role of CCDC6 in thyroid carcinogenesis is also supported by recent investigations showing that CCDC6 is involved in the protection of genome integrity." (PMID 25970781, 2015). "CCDC6 gene is often found rearranged to RET and to genes other that RET in thyroid and non-thyroid human neoplastic diseases." (PMID 22655027, 2012). "Thyroid disease in the patient’s family, Hashimoto’s disease, and hypothyroidism, as well as the type of thyroidectomy, the need for indicating RAI, and smaller tumor size, clustered quite well with gene fusions related to RET, CCDC6, MET, EML4, and ALK." (PMID 39409115, 2024).
bladder cancer (3 papers, 2019 to 2023). "In bladder cancer cells with HR defects caused by CCDC6 depletion (native or induced upon USP7 inhibitor addition) we observed that RRx-001, by exposing cancer cells to reactive oxygen species, enhanced the sensitivity to PARP-inhibitor drugs, as supported by the DRI value (DRI > 1)." (PMID 30786932, 2019). "In a recent study, P5091, an inhibitor of USP7, promoted CCDC6 degradation and sensitized bladder cancer cells to the cytotoxic effect of the PARP-inhibitor olaparib." (PMID 37497216, 2023). "Most importantly, preclinical studies indicate that the attenuation of CCDC6 in lung, pleural, prostate and bladder cancer determines cells sensitivity to inhibitors of PARP1/2 enzymes." (PMID 34841108, 2021). "The immunoblot with anti-CCDC6 antibody indicated that the CCDC6 half-life was reduced upon P5091 pretreatment in bladder cancer cells." (PMID 30786932, 2019). "P5091 determining CCDC6 degradation promoted bladder cancer cells sensitivity to PARP-inhibitor drugs." (PMID 30786932, 2019). "In our study, we reported that 30% of primary bladder carcinoma samples (N = 46) exhibited low or undetectable staining of the CCDC6 protein." (PMID 30786932, 2019). "USP7 has been reported to modulate CCDC6 levels in bladder cancer and lung neuroendocrine cancers." (PMID 37497216, 2023). "Moreover, preclinical studies indicates that the attenuation of CCDC6 in lung, pleural, prostate and bladder cancer cells confer sensitivity to inhibitors of PARP1/2." (PMID 34841108, 2021). "Indeed, in bladder cancer cells P5091 by reducing CCDC6 half-life affected the DSBs DNA repair and determined PARP-inhibitor sensitivity." (PMID 30786932, 2019). "So, out of 46 bladder cancer tumor samples, we could identify a sub-group of high grade bladder cancers with a low expression of CCDC6 and a moderate expression of USP7 (cluster 1), and a sub-group of high grade tumors with higher expression of both the proteins (cluster 3)." (PMID 30786932, 2019). "Interestingly, the scores compared to the tumors grade allowed stratification of the high grade bladder cancer in two clusters, on the basis of CCDC6 expression levels, which may be target for personalized patients treatment, in the future." (PMID 30786932, 2019). "Treatment with USP7 inhibitor determined a significant decrease of the GFP positive cells, compared to non-treated cells, suggesting that the reduction of CCDC6 levels affected the DNA repair by HR in bladder cancer cells." (PMID 30786932, 2019).
pancreatic cancer (3 papers, 2021 to 2022). "BLU-667 is a highly specific RET inhibitor developed for the treatment of tumors with RET mutations and rearrangements, including NCOA4-RET and CCDC6-RET fusions, as observed in two of the analyzed pancreatic tumors." (PMID 33441414, 2021). "Based on the HPA database, immunohistochemistry suggested that CAST, CCDC6, and ERLIN1 protein expression was lower in normal pancreatic tissues but higher in pancreatic cancer tissues." (PMID 35938160, 2022).
acute lymphoblastic leukemia (2 papers, 2019 to 2022). Leukemia with an acute onset, characterized by the presence of lymphoblasts in the bone marrow and the peripheral blood. "We report the case of a patient with B-Cell Acute Lymphoblastic Leukemia (ALL) who was found to harbor a gene fusion involving the CCDC6 and RET genes." (PMID 31850206, 2019).
colon carcinoma (2 papers, 2015 to 2017). "To further study the role of E3-Ubl FBXW7 in the regulation of endogenous CCDC6 protein during the cell cycle we employed the HCT116 FBXW7−/− colon cancer cells." (PMID 25885523, 2015). "Recently, we have reported that low levels of CCDC6 associates with an impariment of Homologous Recombination (HR) mechanisms affecting cells behaviour and cells sensitivity to PARP inhibitors treatment in lung and colon cancer models." (PMID 28415632, 2017). "Recently, we have reported that low levels of CCDC6 associates with defects in DNA repair by Homologous Recombination (HR) affecting cells behaviour and cells sensitivity to PARP inhibitors treatment in lung and colon cancer models." (PMID 28415632, 2017). "In previous studies, we have reported that low levels of CCDC6 protein sensitize NSCLC and colon carcinoma cells to the PARP inhibitor olaparib." (PMID 28415632, 2017).
Hashimoto’s disease (2 papers, 2022 to 2024). "RET and CCDC6 fusions were associated with type of thyroidectomy, RAI therapy, smaller tumor size, and history of Hashimoto’s disease." (PMID 39409115, 2024). "For instance, RET and CCDC6 fusions clustered with variables such as type of thyroidectomy, the need for RAI therapy, smaller tumor size, Hashimoto’s disease, and hypothyroidism." (PMID 39409115, 2024).
lung neuroendocrine tumor (2 papers, 2017 to 2019). "The identification of CCDC6 as a novel USP7 substrate has provided the rationale to establish that the USP7 inhibitor, P5091, by downregulating CCDC6 protein, can modulate the PARP-inhibitors sensitivity in lung neuroendocrine tumors." (PMID 28415632, 2017). "Moreover, we have reported a combined effect of the inhibitors of USP7 and PARP enzymes in the treatment of lung neuroendocrine tumor cells expressing USP7 and CCDC6 proteins." (PMID 28415632, 2017).
osteoarthritis (2 papers, 2021 to 2023). A noninflammatory degenerative joint disease occurring chiefly in older persons, characterized by degeneration of the articular cartilage, hypertrophy of bone at the margins and changes in the synovial membrane. "Overall, CCDC6 represents an osteoarthritis susceptibility gene, deletion of which may contribute to development of osteoarthritis by actions in both cartilage and the synovium." (PMID 33473114, 2021).
prostate tumors (2 papers, 2017 to 2019). "For the purpose of assessing CCDC6 expression levels in a heterogeneous group of human prostate tumors, we analysed 28 samples from patients who underwent surgical tumor resection without any previous treatment." (PMID 28415632, 2017). "Appreciable levels of CCDC6 and USP7 proteins have been observed in a series of prostate tumor cell lines independently of the expression of androgen receptor." (PMID 28415632, 2017). "Interestingly, we have detected targettable levels of USP7 and CCDC6 in 68% of analysed tumors, in a Tissue Micro Array (TMA) of 28 primary prostate tumors." (PMID 28415632, 2017). "Moreover, the inhibition of USP7 enzyme could be considered an ideal treatment, in combination with the PARP inhibitors, in both hormone-sensitive and androgen-resistant prostate tumors that express USP7 and CCDC6." (PMID 28415632, 2017). "Thus, CCDC6 and USP7 might represent novel predictive biomarkers for the combined treatment of the USP7 inhibitors and PARP inhibitors in both hormone-sensitive and androgen-resistant prostate tumors." (PMID 31242618, 2019).
thyroid nodule (2 papers, 2023 to 2025). A small circumscribed mass in the THYROID GLAND that can be of neoplastic growth or non-neoplastic abnormality. "In one unique case of a female, different multiple mutations were found in her three thyroid nodules: CCDC6/RET + NRAS Q61R in the first nodule, CCDC6/RET + KRAS G13D in the second nodule, and NRAS Q61R + PTEN Q245* in the third nodule." (PMID 37882481, 2023). "Therefore, the targets widely recognized and recommended by scholars at home and abroad were selected to compose a 6-gene test panel for thyroid nodule diagnosis, including BRAF V600E mutation, TERT mutation, and gene fusions (CCDC6-RET, NCOA4-RET, ETV6-NTRK3, EML4-NTRK3, STRN-ALK, and PAX8/PPARG)." (PMID 40586006, 2025).
Arthritis (1 paper, 2021). Inflammation of a joint. "The top-ranked genes associated with arthritis and skeletal disease in humans were Pitx1, coiled-coil domain containing 6 (Ccdc6), HECT and RLD domain containing E3 ubiquitin protein ligase family member 1 (Herc1), nebulette (Nebl), Sh3bp4, and Zfp341." (PMID 33473114, 2021).
breast tumors (1 paper, 2025). "We identified 34 differentially expressed genes in metastatic breast tumors, with CCDC6, PKIA, UACA, and PFKP significantly upregulated (p < 0.05)." (PMID 40821334, 2025).